FAP (fibroblast activation protein alpha)
Diseases named in the same sentence as FAP in open-access papers (continued):
Sharing a sentence is not in itself a finding about the gene and the disease.
glioma (continued). "Finally, we have shown that ECM produced by FAP+ pericyte‐like cells enhances the migration of glioma cells including glioma stem‐like cells, promotes their adhesion, and activates focal adhesion kinase (FAK) signaling." (PMID 38705944, 2024). "In terms of IDH mutation status, FAP level was slightly lower in patients with IDH-mutant glioma compared to the IDH-wildtype, but the difference was not statistically significant (Fig. 1IIIa, P = 0.1634)." (PMID 37864148, 2023). "Therefore, FAP is a promising therapeutic target and imaging target for glioma due to its specific expression." (PMID 36382346, 2023). "In conclusion, FAP predicts a poor prognosis for glioma patients and might serve as a biomarker for predicting overall survival." (PMID 36382346, 2023). "However, the absolute uptake of FAP for tumor was low and the tumor-to-background ratio was high, lower uptake of FAP with a higher tumor-to-background ratio were observed in gliomas in other brain studies." (PMID 39355049, 2023). "The integration of serial serum FAP test results with neuroimaging enhances the precision of early glioma recurrence detection, underscoring the potential of combining tumor markers with imaging as a viable approach in the clinical diagnosis of glioma." (PMID 37864148, 2023). "FAP expression in gliomas promotes tumor progression, though serum FAP levels vary." (PMID 37864148, 2023). "Additionally, our research reveals substantial variations in serum FAP levels among gliomas, with a notable elevation observed in a considerable proportion of high-grade gliomas compared to low-grade gliomas." (PMID 37864148, 2023). "[99mTc]Tc-iFAP imaging resolution and contrast were good enough for the high-grade glioma, which could allow the performing of non-invasive diagnoses to differentiate between low- and high-grade gliomas based on their distinct FAP expression." (PMID 35745648, 2022). "However, in glial tumors, FAP levels correlate with the grade and thus the overexpression is associated with a poor prognosis." (PMID 34638433, 2021). "Besides being dose-dependent, TGFbeta-1-mediated upregulation of FAP protein concentration and FAP enzymatic activity in human glioma cells was also time-dependent." (PMID 33494271, 2021). "We further tested the effect of FAP+ mesenchymal cells on glioma cells." (PMID 34282761, 2021). "Thus, mesenchymal transcription factors such as Twist and the autocrine and paracrine TGFbeta-1 signaling described in the current work contribute to the regulation of FAP expression in glioma cells." (PMID 33494271, 2021). "Permanent human glioma cell lines U87, U251 and U118 displayed detectable baseline FAP enzymatic activity and FAP protein which dose-dependently increased when the cells were cultured in the presence of TGFbeta-1 at concentrations ranging from 0.2 ng⋅mL−1 to 10 ng⋅mL−1." (PMID 33494271, 2021). "To elucidate the role of FAP+ stromal cells in the perivascular microenvironment of GBMs, we tested whether FAP+ mesenchymal cell cultures affect endothelial and glioma cells by secreted mediators and by direct cell-to-cell interactions." (PMID 34282761, 2021). "Our experiments suggest that perivascularly localised FAP+ mesenchymal cells may contribute to the vascular tropism of glioma cells and enhance their proliferation." (PMID 34282761, 2021). "In addition, glioma cell growth was modestly increased in a direct co-culture as well as under the influence of soluble factors released by FAP+ mesenchymal cells." (PMID 34282761, 2021). "Collectively, these studies support the notion that various mesenchymal cell types in the GBM microenvironment, including a subpopulation of FAP+ mesenchymal cells, may facilitate growth and characteristic perivascular spreading of glioma cells." (PMID 34282761, 2021). "Moreover, the TGFbeta-1-treated U87 glioma cells also displayed a time-dependent upregulation of FAP mRNA." (PMID 33494271, 2021).
glioma (continued). "We further present evidence of FAP regulation by TGFbeta-1 secreted by glioma cells." (PMID 33494271, 2021). "Moreover, data revealed that FAP enabled glioma cell invasion through brain tissue suggesting its role in tumor cell invasion by facilitating the degradation of the brain parenchyma." (PMID 32806623, 2020). "We hypothesized that high-grade gliomas may coexist with high FAP and GFAP expression." (PMID 39629119, 2024). "However, there was significant FAP expression heterogeneity among identical graded gliomas." (PMID 37864148, 2023). "Together, according to our analysis, high FAP expression predicts a poorer prognosis for glioma patients, elevated FAP expression correlates with non‐codeletion of 1p19q, wild‐type IDH1 status, and old age, and FAP might serve as a biomarker for predicting overall survival." (PMID 36382346, 2023). "Additionally, while examining human tumor samples and tumor cells lines to understand the relevance of FAP expression, Busek and colleagues discovered elevated levels of FAP protein in most human high-grade gliomas with a mesenchymal subtype and in several glioma tumor cells lines." (PMID 32806623, 2020). "Principal component analysis showed a close relation between the two FAP+ pericyte‐like cell cultures and HBVP, while ECM produced by U87 glioma cells was highly separated from these cell cultures." (PMID 38705944, 2024). "FAP‐CAR‐T cells exhibited target specificity against model cell lines and potent cytotoxicity against patient‐derived glioma neural stem cells, even when only a subpopulation expressed FAP, indicating a bystander killing mechanism." (PMID 38975278, 2024). "Taken together, our findings establish FAP+ pericyte‐like cells as crucial producers of a complex ECM rich in collagen I and fibronectin, facilitating the dissemination of glioma cells through FAK activation." (PMID 38705944, 2024). "In glioma cells, this regulation is mediated by TGFbeta type I receptor and canonical SMAD and involves the activation of FAP gene transcription." (PMID 33494271, 2021). "Since this A8301- and A7701-sensitive fraction of baseline FAP protein and FAP enzymatic activity could be due to upregulation via autocrine TGFbeta-1 signaling, we investigated the secretion of endogenous TGFbeta-1 in U87 and U251 glioma cells and in human brain vascular pericytes (HBVP)." (PMID 33494271, 2021). "Furthermore, the researchers demonstrated that glioma stem cells could differentiate into tumor pericytes, and analysis of the Ivy GBM dataset showed intense FAP expression in areas of microvascular proliferation, suggesting the angiogenetic role of FAP expression on glioma stem cells in GBM." (PMID 34068501, 2021). "To better understand the role of FAP+ stromal cells in the perivascular niche, we isolated these cells from GBM tissue and analysed their effect on endothelial and glioma cells." (PMID 34282761, 2021). "Fibroblast activation protein alpha (FAP), a 170 kDa type II transmembrane serine protease was observed to be expressed on glioma cells and within the glioma tumor microenvironment." (PMID 32806623, 2020). "Other studies report on the detection of brain metastases with FAP-specific PET as well and also noting that the lower absolute uptake but higher tumor-to-background ratio observed in glioma also applies there." (PMID 32942573, 2020). "mRNA levels of FAP were significantly elevated in GBM, compared with normal brain and lower grade gliomas (WHO grade II and III)." (PMID 33308315, 2020). "In this work, we show that FAP+ cells are increased in human GBM and have clinical prognostic value in glioma." (PMID 33308315, 2020). "In a set of 39 human glial neoplasms using quantitative RT-PCR we found a significant correlation between TWIST1 and SNAI2 (r = 0.72; p = 0.001) and TWIST1 and FAP alpha (r = 0.57, p = 0.001) message levels." (PMID 20646316, 2010).
glioma (continued). "We identify FAP+ pericyte‐like cells as the main producers of ECM rich in COLI and FN1 in GBM and provide evidence that this ECM facilitates migration and adhesion of glioma cells through FAK activation." (PMID 38705944, 2024). "Collectively, these results suggest that FAP+ pericyte‐like cells abundantly produce and deposit fibrillar ECM proteins, whereas glioma cells can express fibrillar ECM proteins, but their ability to deposit these proteins in the extracellular space is strongly limited." (PMID 38705944, 2024). "The findings suggest that patients with tumor progression exhibit significantly elevated FAP levels compared to those without recurrent glioma, thereby highlighting the potential of blood tumor markers for glioma as a sensitive tool for early diagnosis." (PMID 37864148, 2023). "Taken together, we successfully isolated FAP+ cells from human GBMs that express mesenchymal markers, are non-tumorigenic, and in most cases lack genetic aberrations characteristic of glioma cells, which suggests that they are non-malignant mesenchymal cells." (PMID 34282761, 2021). "Conditioned media from FAP+ mesenchymal cells and HBVP promoted chemotaxis of glioma cells." (PMID 34282761, 2021). "FAP+ cells were efficiently propagated in conditions suitable for pericytes, expressed mesenchymal markers PDGFRβ, αSMA, and TE-7, but were negative for glioma (GFAP) and endothelial (vWf) markers." (PMID 34282761, 2021). "Using FAP-specific PET imaging may allow a noninvasive distinction between low-grade IDH-mutant and high-grade gliomas." (PMID 34858834, 2021). "Other genes associated with mesenchymal phenotypes and glioma invasion, not yet formally linked to EMT, included laminin, alpha 4 (LAMA4) and fibroblast activation protein alpha (FAP)." (PMID 20646316, 2010). "Irrespective of the methylation status of the MGMT promoter, elevated levels of FAP were observed in gliomas of all grades, regardless of whether they were methylated or unmethylated." (PMID 37864148, 2023). "Although FAP has been extensively investigated as a biomarker in various cancer types, there is currently a lack of studies reporting on the longitudinal monitoring of glioma progression using sequential serum FAP." (PMID 37864148, 2023). "Additionally, a disparity in FAP expression was observed between GBM and grade 2 and 3 glioma." (PMID 37864148, 2023). "We were able to effectively propagate FAP+ cells in culture conditions used for human brain vascular pericytes (HBVP); on the other hand, we did not succeed in maintaining them in DMEM supplemented with 10% FCS, which is traditionally used for culturing fibroblasts and glioma cells." (PMID 34282761, 2021). "The biochemical basis of the very low baseline FAP levels and absent or negligible upregulation of FAP after treatment with recombinant TGFbeta-1 in glioma stem-like cells and human umbilical vein endothelial cells (HUVEC) is, at present, unknown." (PMID 33494271, 2021). "Moreover, they suggest the involvement of the FAP+ pericyte‐like cells in the secretion of essential basement membrane proteins, which together with COLI and FN1 may create a permissive environment for glioma cell dissemination." (PMID 38705944, 2024). "Decellularized ECMs were prepared in four replicates from FAP+ pericyte‐like cells (46A and 80A), HBVP, U87, and U251 glioma cells; gelatin‐coated plates incubated without cells processed in the same way were used as controls." (PMID 38705944, 2024). "Since FAP is typically overexpressed in higher grade glioma, especially GBM, the previously observed negative correlation of the FAP expression level with survival may have been caused by the large proportion of GBM cases with high FAP expression in the analysis group." (PMID 34068501, 2021). "Studies on the practical relevance between FAP expression level and prognosis in GBM patients rather than glioma patients are contradictory, and more data are needed." (PMID 34068501, 2021).
glioma (continued). "Using Western blot analysis with specific anti-pSmad2 antibodies, we demonstrated that both the FAP-upregulating U87 glioma cells and FAP-non-upregulating AZVU001A glioma stem-like cells were capable of rapidly phosphorylating the Smad2 protein when exposed to TGFbeta-1." (PMID 33494271, 2021).
liver fibrosis (27 papers, 2010 to 2026). "We have also previously demonstrated the potential for the use of circulating fibroblast activation protein alpha (cFAP) as a diagnostic biomarker for liver fibrosis, based on which the fibroblast activation protein (FAP) index can be calculated." (PMID 38201904, 2023). "Thus, FAP Index is a novel, fibrogenesis-relevant, rapid, robust diagnostic tool suited to increasing the efficiency of liver fibrosis triage in primary care." (PMID 41698414, 2026). "Fibroblast activation protein (FAP), highly expressed by activated HSCs, is a pivotal player in the pathogenesis of liver fibrosis." (PMID 42213756, 2026). "In this study, in vivo and in vitro experiments were performed to verify the promoting effects of IL-17a administration, IL-17a overexpression, and FAP upregulation in HSCs on liver fibrosis and liver tumorigenesis." (PMID 38740736, 2024). "FAP is a well-established marker for activated fibroblasts, and its serine protease activity promotes liver fibrosis by activating HSCs and promoting macrophage infiltration after liver injury." (PMID 39656528, 2024). "At the same time, when an FAPα inhibitor is administered to mice with liver fibrosis, MMP-2, -9, -13, and TIMPs are decreased." (PMID 38136590, 2023). "And pharmacological FAP inhibition alleviates liver fibrosis in chronic liver injury via attenuating macrophage infiltration and activation, macrophage-derived inflammation contributes to the development of RHF." (PMID 37932744, 2023). "The FAP-liberated melittin was shown to be capable of killing aHSC and alleviating fibrosis in mouse models of liver fibrosis induced by BDL, CCl4, or CDAHFD." (PMID 35314685, 2022). "Taken together, the present study demonstrates that BR103354 acts as a selective and potent FAP inhibitor and improves insulin resistance, glucose tolerance, and hepatic fibrosis in various animal models, possibly via FAP inhibition." (PMID 33277568, 2020). "In view of this insufficient situation, we hypothesized that FAP imaging might be useful as a non-invasive imaging method for the assessment of liver fibrosis." (PMID 40048016, 2025). "Modeling liver fibrosis and the subsequent suppression of FAPα in mice using a specific inhibitor (FAPi) showed a decrease in the level of collagen, αSMA+ myofibroblasts, ALT and AST levels, and key transcripts associated with fibrogenesis under the influence of the inhibitor." (PMID 38136590, 2023). "In the model of CCl4-induced liver fibrosis, the amount and expression of type 1 and 3 collagens, as well as osteopontin, decreases with the introduction of the FAPα enzymatic activity inhibitor during the progression of fibrosis, but not during the remodeling stage." (PMID 38136590, 2023). "We next tested whether expression of FAP was increased in a liver fibrosis model, and if so, whether promelittin on PRL could be cleaved in the liver." (PMID 35314685, 2022). "Upregulation of FAPα in αSMA+ activated HSCs has been observed in liver fibrosis and cirrhosis." (PMID 35951441, 2022). "Other reports indicate that hepatic stellate cells, tissue-specific pericytes in the liver, overexpress FAP following activation and promote angiogenesis in liver fibrosis and hepatocellular carcinoma by increasing the levels of Angiopoietin-1 and Angiopoietin-2." (PMID 34282761, 2021). "DPP4 and FAP have established roles in metabolism, fatty liver, liver fibrosis and cirrhosis." (PMID 34771657, 2021). "FAP is also highly expressed in active fibroblastic cells in cancer and hepatic fibrosis." (PMID 26359667, 2015). "FAP may facilitate extracellular matrix remodeling mediated by hepatic stellate cells, and its expression during cirrhosis correlates with the severity of liver fibrosis." (PMID 41594225, 2026). "However, still little is known about the efficacy of FAP imaging in liver fibrosis." (PMID 40048016, 2025).
liver fibrosis (continued). "Moreover, FAP plasma abundance changes have been associated with liver fibrosis not only in virus-related cirrhosis but also in non-cirrhotic patients with MASLD in diabetes and obesity." (PMID 39017916, 2025). "Interestingly, other studies showed an increase of circulating FAP in patients with liver fibrosis and support the hypothesis that the liver constitutes a major source of elevated circulating FAP." (PMID 39188902, 2024). "The 2D-SWE-derived EQI Median exhibited moderate-to-weak positive correlations with several established non-invasive liver fibrosis scoring systems, including the FIB-4 index, APRI, NFS, and FAP index." (PMID 38201904, 2023). "Moderate-to-weak positive correlations were observed between 2D-SWE-derived EQI Median and established non-invasive liver fibrosis scoring systems, including the FIB-4 index, APRI, NFS, and FAP index." (PMID 38201904, 2023). "Although we demonstrated the antifibrotic efficacy of PRL in a liver fibrosis model, the selective activation of PRL by FAP suggests the potential of PRL for the treatment of various fibrotic diseases in which FAP is overexpressed." (PMID 35314685, 2022). "In human, increased plasma DPP4 and FAP enzyme activities have been reported in patients with NAFLD, liver fibrosis and cirrhosis." (PMID 34771657, 2021). "Further, FAP and MMP‐1 have been shown to be positively correlated with the degree of liver fibrosis in mice." (PMID 32311840, 2020). "FAP imaging is possibly an effective method for the non-invasive detection of liver fibrosis especially in the early phase, which is frequently accompanied by lipogenic changes and slightly altered serum parameters." (PMID 40048016, 2025). "The role of the FAP protein and its pharmacological inhibition as a potential therapy for liver fibrosis are not clearly examined." (PMID 38434195, 2023).